SPNS1 (SPNS lysolipid transporter 1, lysophospholipid)
Description:
Plays a critical role in the phospholipid salvage pathway from lysosomes to the cytosol. Mediates the rate-limiting, proton-dependent, lysosomal efflux of lysophospholipids, which can then be reacylated by acyltransferases in the endoplasmic reticulum to form phospholipids. Selective for zwitterionic headgroups such as lysophosphatidylcholine (LPC) and lysophosphatidylethanolamine (LPE), can also transport lysophosphatidylglycerol (LPG), but not other anionic lysophospholipids, sphingosine, nor sphingomyelin. Transports lysophospholipids with saturated, monounsaturated, and polyunsaturated fatty acids, such as 1-hexadecanoyl-sn-glycero-3-phosphocholine, 1-(9Z-octadecenoyl)-sn-glycero-3-phosphocholine and 1-(4Z,7Z,10Z,13Z,16Z,19Z-docosahexaenoyl)- sn-glycero-3-phosphocholine, respectively. Can also transport lysoplasmalogen (LPC with a fatty alcohol) such as 1-(1Z-hexadecenyl)-sn-glycero-3-phosphocholine. Lysosomal LPC could function as intracellular signaling messenger. Essential player in lysosomal homeostasis. Crucial for cell survival under conditions of nutrient limitation. May be involved in necrotic or autophagic cell death.
Synonyms: SPIN1; HSpin1; nrs; SPINL; PP2030; LAT; SLC63A1; SLC62A1
Tractability: Small molecule: a structure with a bound ligand is known. Antibody: UniProt predicts a signal peptide or a membrane-spanning region. PROTAC: its protein half-life has been measured.
Gene: Protein-coding gene on chromosome 16 (28,974,221 to 28,984,548, forward strand). Ensembl gene ENSG00000169682.
Subcellular location: Lysosome membrane; Mitochondrion inner membrane
Subcellular location (Human Protein Atlas): Vesicles; Cytosol; Golgi apparatus; Nucleoli fibrillar center
Gene Ontology:
Molecular function: lysophospholipid:sodium symporter activity; protein binding; transmembrane transporter activity
Biological process: lysophospholipid transport; phospholipid efflux; lipid transport; transmembrane transport
Cellular component: lysosomal membrane; lysosome; membrane; mitochondrial inner membrane
Genetic constraint (gnomAD): Loss-of-function variants: 22 observed, 48.16 expected, observed/expected ratio (o/e) 0.46, 90% interval 0.32 to 0.65. The upper end of that interval is the gene's LOEUF score, 0.65, which puts it in group 2 of 6, group 1 being the genes least tolerant of losing a copy. Missense variants: 576 observed, 709.37 expected, observed/expected ratio (o/e) 0.81, 90% interval 0.76 to 0.87. Synonymous variants: 295 observed, 304.2 expected, observed/expected ratio (o/e) 0.97, 90% interval 0.88 to 1.07.
Homologues: Orthologues: guinea pig SPNS1 (95% identical), macaque SPNS1 (94% identical), pig SPNS1 (94% identical), mouse Spns1 (94% identical), rat Spns1 (93% identical), rabbit SPNS1 (92% identical), dog SPNS1 (92% identical), chimpanzee SPNS1 (90% identical), tropical clawed frog spns1 (67% identical), zebrafish spns1 (64% identical), Drosophila melanogaster spin (48% identical), Caenorhabditis elegans spin-1 (37% identical), and 3 more. Paralogues in human: SPNS2 (51% identical), SPNS3 (49% identical).
Diseases named in the same sentence as SPNS1 in open-access papers:
SPNS1 is named in the same sentence as 29 diseases in open-access papers, as found by Europe PMC text mining. Sharing a sentence is not in itself a finding about the gene and the disease. The quoted sentences say what the papers report.
lysosomal storage disease (4 papers, 2021 to 2025). A metabolic disorder caused by mutations in proteins critical for lysosomal function, including lysosomal enzymes, lysosomal integral membrane proteins, and proteins involved in the post-translational modification and trafficking of lysosomal proteins. "This represents a lysosomal storage disease caused by SPNS1 variants and defines a gene-disease association." (PMID 40608416, 2025). "Taken together, our study reports a lysosomal storage disease resulting from inactivating mutations in SPNS1 that revealed crosstalk between lysosomal lysophospholipid transport with the regulation of cellular cholesterol and TAG homeostasis." (PMID 40608416, 2025). "Collectively, our findings indicate that the deficiency of SPNS1 results in lysolipid accumulation in the lysosomes, causing the pathological conditions that resemble lysosomal storage diseases." (PMID 38451736, 2024). "The deletion of lysolipid transporter SPNS1 in murine modles causes lipid accumulation, resulting in embryonic lethality and lysosomal storage disease." (PMID 38451736, 2024). "SPNS1 encodes a lysosomal efflux transporter that regulates mTOR signaling and whose loss‐of‐function is associated with lysosome storage disorders." (PMID 36124427, 2022). "The SPNS1 gene is known to be associated with a number of human diseases, including T2D and obesity, which is mainly associated with lysosome storage disorder (LSD)." (PMID 33927693, 2021). "Deficiency of SPNS1 results in phenotypes reminiscent of lysosomal storage diseases in mice." (PMID 38451736, 2024). "Since deficiency of Spns1 in mice causes lysosomal storage disease, we speculate that a defect in the function of SPNS1 in humans also results in lysosomal storage disease." (PMID 38451736, 2024). "In the attempt to understand the pathogenesis of this newly characterized lysosomal storage disease, we discovered additional roles of SPNS1 in maintaining cellular lipid homeostasis other than phospholipid salvage." (PMID 40608416, 2025). "Therefore, accumulation of sphingosines in the livers of Spns1-KO mice might be a major part of the pathogenesis, suggesting that lowering sphingosine accumulation would have beneficial effects on the functions of liver in lysosomal storage diseases." (PMID 38451736, 2024). "Lack of SPNS1 results in pathological conditions similar to lysosomal storage diseases in mice." (PMID 38451736, 2024).
Parkinson (2 papers, 2024 to 2025). "Specific common coding variants in SPNS1 and MLX may be involved in Parkinson’s disease, and burden tests of rare variants further support that CNIP3, LSM7, NUCKS1 and the polyol/inositol phosphate biosynthetic pathway are associated with the disease." (PMID 37804111, 2024).
breast carcinoma (1 paper, 2021). "However, the function of MLST8 and SPNS1 in breast cancer was still unknown." (PMID 33796128, 2021).
depression (1 paper, 2015). "The HTR2A gene codes for a serotonin receptor and is associated with behavioral traits, schizophrenia and depression, KCNAB3 encodes a subunit of a voltage-sensitive potassium channel, and SPNS1 codes for the Spinster-1 protein implicated in apoptosis in the Drosophila central nervous system." (PMID 26607552, 2015).
Intellectual disability (1 paper, 2024). "We identified 3 patients with a homozygous variant of SPNS1 who exhibit clinical symptoms, including neurodevelopmental delay, intellectual disability, and speech problems, but lack the vision problems." (PMID 38451736, 2024).
iron deficiency (1 paper, 2024). "Yet exogenous iron load suppressed endocytosis and mimicked Spns1 KO phenotype, while iron deficiency or deletion of DMT1 reversed the failure of endocytosis." (PMID 39265081, 2024).
liver cancer (1 paper, 2021). An epithelial or non-epithelial malignant neoplasm that arises from the liver. "The expression of ATIC, HDAC1, RHEB, SPNS1 and TMEM74 in liver cancer tissues was significantly higher than that in normal liver tissues." (PMID 34803509, 2021).
lung carcinoma (1 paper, 2022). "Altogether, these experiments confirm and extend our screen results and demonstrate that loss‐of‐function of PLAC8 and SPNS1 specifically impairs viral entry of S‐typed lentiviruses in human lung cancer cells." (PMID 36124427, 2022). "By contrast, SPNS1 shows overall low levels of expression in lung epithelial cell types and it is not particularly enriched in any cell population, consistently with our previous observations in different lung cancer cell lines and its putative role as a ubiquitous nonlimiting host factor." (PMID 36124427, 2022).
prostate carcinoma (1 paper, 2015). A carcinoma that arises from epithelial cells of the prostate gland. "The exosomal (CD9- CD81-SCARB2) (average enrichment 2.40) and lysosomal (CTSD- LAMP2- CTSZ- SPNS1- PSAP) (average enrichment 4.15) proteins were also enriched in exosomes from prostate cancer patients." (PMID 26196085, 2015).
tumor (3 papers, 2014 to 2021). "Regarding SPNS1, only a few studies have been conducted; however, its relationship with tumours has not been reported." (PMID 34087900, 2021).
infection (2 papers, 2022 to 2023). The state of being infected such as from the introduction of a foreign agent such as serum, vaccine, antigenic substance or organism. "In these studies, loss‐of‐function of SPNS1 and PLAC8 using different CRISPR vectors significantly reduced the infection susceptibility of Calu1ACE2 cells to S‐typed lentiviruses." (PMID 36124427, 2022). "While knockdown of KEAP1, GPR89A/B, and SPNS1 initially decreased interferon stimulation in our experiments, it is conceivable that these factors have a secondary role in protecting the population from infection in long-term cultures." (PMID 37803001, 2023). "Notably, all PLAC8 and SPNS1 KO cell lines showed a dramatic reduction in infection efficiency using S‐typed lentiviruses, reaching higher fold‐change levels than any positive control (except for ACE2‐KO)." (PMID 36124427, 2022). "In summary, we have demonstrated herein that SPNS1 and PLAC8 are host factors necessary for SARS‐CoV‐2 entry and that PLAC8 is a limiting factor that enables human pulmonary cells for infection." (PMID 36124427, 2022). "KEAP1, GPR89A/B, and SPNS1, which were previously found to be protective when knocked out5,7,9, did not alter infection dynamics within our study." (PMID 37803001, 2023). "Notably, SPNS1 overexpression did not have an overall impact on infection efficiency, showing only a modest increase in H226, H1299, H2009, and SW900 cells." (PMID 36124427, 2022). "Notably, Calu1ACE2 and H1299ACE2 cell lines showed the highest levels of infection with S‐typed lentiviruses, while ACE2 overexpression did not change protein levels of PLAC8 or SPNS1 in any cell line." (PMID 36124427, 2022).
cancer (1 paper, 2023). A tumor composed of atypical neoplastic, often pleomorphic cells that invade other tissues. "Because choline is highly enriched in rapidly proliferating tumors that require it for lipid biosynthesis, it follows that cancer cells might induce SPNS1 expression as a cellular strategy to salvage phospholipids for biomass production." (PMID 37075117, 2023). "SPNS1 could therefore be a candidate therapeutic target in cancer and the treatment of viral illnesses." (PMID 37075117, 2023).
inflammation (1 paper, 2025). Aberrant reaction of the microcirculation characterized by movement of fluid and leukocytes from the blood into extravascular tissues. "Spns1 deficiency in mice is embryonically lethal, whereas knockdown or genetic deletion of Spns1 in adult mice results in pathologies including liver inflammation, demyelination in brain, and skeletal muscle atrophy." (PMID 40608416, 2025).
SPNS1 also shares sentences with these, for which no sentence is quoted: Obesity (2 papers); atherosclerosis (1); COVID-19 (1); genetic disease (1); Glucose intolerance (1); hepatoma (1); Hypertension (1); infectious disease (1); lung adenocarcinoma (1); microcephaly (1); neurodegenerative disease (1); Neurodevelopmental delay (1); Niemann-Pick type C disease (1); pancreatic cancer (1); schizophrenia (1); viral infection (1).